PMM2 (phosphomannomutase 2)
Description:
Involved in the synthesis of the GDP-mannose and dolichol-phosphate-mannose required for a number of critical mannosyl transfer reactions.
Synonyms: PMM 2; CDGS; CDG1a; PMI; PMI1; LOC100130283; CDG1
Tractability: Small molecule: a structure with a bound ligand is known; a high-quality ligand is known. PROTAC: ubiquitination databases record sites on it; its protein half-life has been measured; a small molecule that binds it is known.
Target class: Isomerase; Enzyme
Gene: Protein-coding gene on chromosome 16 (8,788,823 to 8,862,534, forward strand). Ensembl gene ENSG00000140650.
Subcellular location: Cytoplasm
Subcellular location (Human Protein Atlas): Cytosol; Nucleoplasm; Microtubules; Primary cilium; Primary cilium tip
Pathways (Reactome):
Disease: Defective PMM2 causes PMM2-CDG
Metabolism of proteins: Synthesis of GDP-mannose
Gene Ontology:
Molecular function: phosphomannomutase activity; protein binding
Biological process: GDP-mannose biosynthetic process; glycoprotein biosynthetic process; mannose metabolic process; protein N-linked glycosylation
Cellular component: cytosol; cytoplasm; neuronal cell body
Genetic constraint (gnomAD): Loss-of-function variants: 16 observed, 10.22 expected, observed/expected ratio (o/e) 1.57, 90% interval 1.03 to 1.94. The synonymous counts are far from expectation, so gnomAD's model fits this gene poorly and the ratio says little. Missense variants: 230 observed, 166.31 expected, observed/expected ratio (o/e) 1.38, 90% interval 1.24 to 1.54. Synonymous variants: 92 observed, 65.93 expected, observed/expected ratio (o/e) 1.4, 90% interval 1.18 to 1.66.
Gene-disease validity (ClinGen):
ClinGen rates the evidence that PMM2 causes each of these diseases.
PMM2-congenital disorder of glycosylation (autosomal recessive): Definitive. The most frequent form of congenital disorder of N-glycosylation and is characterized by cerebellar dysfunction, abnormal fat distribution, inverted nipples, strabismus and hypotonia.
Homologues: Orthologues: chimpanzee PMM2 (99% identical), macaque PMM2 (98% identical), rabbit PMM2 (95% identical), dog PMM2 (94% identical), guinea pig PMM2 (92% identical), rat Pmm2 (92% identical), mouse Pmm2 (90% identical), tropical clawed frog pmm1 (74% identical), zebrafish pmm2 (71% identical), Caenorhabditis elegans F52B11.2 (56% identical), Drosophila melanogaster Pmm2 (53% identical). Paralogues in human: PMM1 (68% identical).
Diseases named in the same sentence as PMM2 in open-access papers:
PMM2 is named in the same sentence as 147 diseases in open-access papers, as found by Europe PMC text mining. Sharing a sentence is not in itself a finding about the gene and the disease. The quoted sentences say what the papers report.
congenital disorder of glycosylation (30 papers, 2013 to 2026). Congenital disorder of glycosylation (CDG) is a fast growing group of inborn errors of metabolism characterized by defective activity of enzymes that participate in glycosylation (modification of proteins and other macromolecules by adding and processing of oligosaccharide side chains). "This missense variant is well-documented as the most common pathogenic variant found in patients with PMM2-associated congenital disorders of glycosylation (CDG-1a)." (PMID 40650005, 2025). "Its deficiency is the most common cause of congenital disorders of glycosylation (CDGs), accounting for the subtype known as PMM2-CDG." (PMID 40572562, 2025). "Mutations of PMM2 result in the PMM2-congenital disorder of glycosylation, which is an inherited condition that affects many parts of the body." (PMID 37428395, 2023). "Biallelic deleterious variants in PMM2 underlie the commonest Congenital Disorder of Glycosylation (CDG) disease (PMM2-CDG)." (PMID 36773065, 2023). "Phosphomannomutase 2 deficiency (PMM2‐CDG) is the most common congenital disorder of glycosylation (CDG)." (PMID 32071842, 2020). "Phosphomannomutase 2 Deficiency (PMM2-CDG) is the most common monogenic congenital disorder of glycosylation (CDG) affecting at least 800 patients globally." (PMID 30530630, 2019). "PMM2 deficiency is the most common congenital disorder of glycosylation (PMM2-CDG)." (PMID 40003995, 2025). "PMM2 deficiency is one of the most common causes of congenital disorder of glycosylation (CDG)." (PMID 36412659, 2022). "Phosphomannomutase 2 deficiency (PMM2-CDG) is the most common congenital disorder of glycosylation (CDG) in Poland." (PMID 34682117, 2021). "Only PMM2 has been associated with human diseases and is responsible for the most common congenital disorder of glycosylation (CDG)." (PMID 31454904, 2019). "The loss of PMM2 function leads to PMM2-CDG (OMIM: 212065; ORPHA: 793180), a congenital disorder of glycosylation (CDG) characterized by defective glycosylation." (PMID 40572562, 2025). "Phosphomannomutase 2-Congenital Disorder of Glycosylation (PMM2-CDG) is a rare genetic disease affecting glycosylation with a multi-systemic impact." (PMID 41050669, 2025). "Phosphomannomutase 2 (PMM2)-congenital disorder of glycosylation (CDG) (previously CDG-Ia; OMIM # 212065) is the most common disorder of protein N-glycosylation in humans, affecting over 1000 patients worldwide." (PMID 40771275, 2025). "Diagnosis of PMM2-CDG, the most common congenital disorder of glycosylation (CDG), relies on measuring carbohydrate-deficient transferrin (CDT) and genetic testing." (PMID 38587076, 2024). "Congenital disorders of glycosylation (CDG) comprise some 160 genetic disorders caused by impaired synthesis of glycoconjugates, with phosphomannomutase deficiency (PMM2-CDG, *601785OMIM) being the most frequent, with more than 1,000 reported patients." (PMID 38129426, 2023). "Some congenital disorders of glycosylation (CDGs) are caused by abnormal sugar nucleotide metabolism, such as defects in GDP-Man (PMM2-CDG) biosynthesis or an unbalanced UDP-Gal/UDP-GlcNAc ratio (PGM1-CDG)." (PMID 35422047, 2022). "PMM2-CDG is the most prevalent congenital disorder of glycosylation (CDG) with only symptomatic therapy." (PMID 33743737, 2021). "Congenital disorders of glycosylation (CDG) are a rapidly growing family of genetic diseases with the phosphomannomutase 2 (PMM2)-CDG being the most common form of CDG." (PMID 33133147, 2020). "Phosphomannomutase 2 - Congenital Disorder of Glycosylation (PMM2-CDG, formerly CDG Ia, ORPHA79318, MIM 212065) is by far the most frequent type of CDG with more than 800 patients reported worldwide in 2009 (about 1:20.000 to 1:50.000 births worldwide)." (PMID 25497157, 2014). "Phosphomannomutase-2 (PMM2) deficiency leads to the prominent Congenital Disorder of Glycosylation (CDG), a rare disease currently lacking effective treatment options." (PMID 41968365, 2026).
congenital disorder of glycosylation (continued). "Phosphomannomutase 2 (PMM2) deficiency causes Congenital Disorder of Glycosylation (PMM2-CDG), but does not have a recognised association with Inflammatory Bowel Disease (IBD)." (PMID 36773065, 2023). "Hypocholesterolemia may also manifest in other disorders, including abetalipoproteinemia types I and II, chylomicron retention disorder, PMM2‐congenital disorder of glycosylation, mevalonic aciduria, 3β‐hydroxy‐Δ5‐C27 steroid dehydrogenase deficiency, Smith–Lemli–Opitz syndrome, and Tangier disease." (PMID 39544692, 2024). "Phosphomannomutase 2 deficiency (PMM2‐CDG, OMIM number: 212065) is the most common congenital disorder of glycosylation (CDG)." (PMID 32071842, 2020). "In particular, NS in infancy or early childhood has been observed in some subtypes of CDG, such as PMM2-CDG (phosphomannomutase 2-congenital disorder of glycosylation) and ALG1-CDG (ALG1-congenital disorder of glycosylation)." (PMID 40868160, 2025). "While epalrestat has a beneficial role in ameliorating phosphomannomutase 2-congenital disorder of glycosylation (PMM2-CDG), the efficacy of epalrestat is undergoing assessment in the clinical trial of PMM2-CDG (NCT04925960)." (PMID 40003995, 2025). "Eighteen out of these 24 participants had diagnostic variants in PMM2 (HGNC:9115) and their phenotypes aligned with congenital disorder of glycosylation had type Ia, rather than polycystic kidney disease with hyperinsulinemic hypoglycemia that is included in the Generation Study." (PMID 40684348, 2025). "The most common congenital glycosylation disorder (CGD) is in fact PMM2 deficiency (PMM2-CDG, MIM#212065), which was formerly known as Congenital Disorder of Glycosylation-Ia, CDG-Ia, or Jaeken syndrome; no CDG described so far is linked to mutations of PMM1." (PMID 24498599, 2013).
Ataxia (21 papers, 2014 to 2025). Ataxia refers to impaired coordination of voluntary muscle movement. "This, together with PMM2 mutations, would enhance the decline of PMM2 enzyme activity, contributing to the development of the ataxia phenotype." (PMID 41199322, 2025). "Phosphomannomutase deficiency (PMM2-CDG) leads to cerebellar atrophy with ataxia, dysmetria, and intellectual deficits." (PMID 38129426, 2023). "Secondary to the atrophy of the cerebellum, patients develop ataxia; PMM2-CDG is associated with the CACNA1A gene gain-of-function mutation that encodes the voltage-gated CaV2.1 channel." (PMID 36295831, 2022). "Recently, a novel mutation in PMCA3 (G733R) has been identified in a patient carrying a defect in phosphomannomutase 2 (PMM2), indicating a possible link between these mutations in generating ataxia phenotype." (PMID 33801794, 2021). "Cerebellar ataxia is the primary diagnostic indicator in patients with PMM2 mutations (PMM2-CDG, also known as CDG-Ia disorder), which is the most frequent CDG." (PMID 30311906, 2018). "We also found three other genes that are differentially expressed due to Fxn knockdown, namely, CSTB, NHLRC1 and PMM2 all of which are associated with other disorders manifesting ataxia." (PMID 29257745, 2017). "We aim to delineate the progression of cerebellar syndrome in children with phosphomannomutase-deficiency (PMM2-CDG) using the International Cooperative Ataxia Rating Scale (ICARS)." (PMID 28915903, 2017). "We also suspected PMM2 mutation as a cause of adult-onset chorea plus ataxia and congenital cognitive decline (case 35), the most common congenital disorder of N-glycosylation, but genetic analyses did not permit such confirmation (only one confirmed PMM2 mutation)." (PMID 37692071, 2023). "It is unclear currently whether these developmental defects would eventually cause neuronal atrophy or degeneration or whether these phenotypes explain aspects of PMM2-CDG–associated ataxia." (PMID 34784297, 2021). "Neural pmm2 knockdown adults have severe ataxia, with profound incoordination, inability to walk in a directed fashion and complete inability to fly." (PMID 26940433, 2016). "We aim to assess the validity of the International Cooperative Ataxia Rating Scale (ICARS) in children and adolescents with genetically confirmed PMM2-CDG deficiency." (PMID 26502900, 2015). "The rational for clinical evaluation of acetazolamide was based on the hypothesis that hypoglycosylation of calcium channels is an underlying pathomechanism of ataxia and SLE in PMM2-CDG patients." (PMID 35955863, 2022). "Although head trauma is a common situation in children with ataxia and hypotonia, due to clumsiness, why only some PMM2-CDG patients develop SLE after cranial trauma is currently unknown." (PMID 34708008, 2021). "The coexistence of both PMCA3 and PMM2 mutations in the patient affected by non-progressive ataxia and muscular hypotonia is of special significance as PMM2 was found to be Ca2+-regulated enzyme." (PMID 33801794, 2021). "We explore the hypothesis of abnormal CaV2.1 function due to aberrant N-glycosylation as a potential novel pathomechanism of SLE and ataxia in PMM2-CDG by using whole-cell patch-clamp, N-glycosylation blockade and mutagenesis." (PMID 29470411, 2018). "Interestingly, some clinical, neuroimaging and neurophysiological features of PMM2-CDG patients and CACNA1A mutated patients are similar, including not only SLE, but also ataxia, ocular motor disturbances, and cerebellar atrophy on MRI." (PMID 29470411, 2018). "In the congenital disorder of glycosylation, type 1a (PMM2-CDG) patients’ phenotype presentation is dominated by neurologic abnormalities such as psychomotor disability, seizures, hypotonia, and ataxia." (PMID 38891946, 2024). "PMM2-CDG can be classified into three forms: the infantile multisystemic form, the late infantile/childhood form presenting with ataxia and intellectual disability and the adult form that presents with stable disability." (PMID 37239976, 2023).
Ataxia (continued). "Cerebellar atrophy and ataxia were found only in ALG1‐CDG and PMM2‐CDG, being present in almost all patients in the latter." (PMID 35279850, 2022). "The disease should, however, be included in the differential diagnosis, especially in the evaluation of patients with seizures, ataxia, areflexia, developmental delay (ALG6-CDG) or be evaluated in individuals diagnosed with PMM2-CDG." (PMID 33440761, 2021). "It has been reported repeatedly that cerebellar ataxia is not progressive in PMM2-CDG, which we observed in our cohort." (PMID 25497157, 2014). "Interestingly, chronically speaking, clinical, neuroimaging, and neurophysiological features of PMM2-CDG and CACNA1A related phenotypes are also similar, including, ataxia, ocular motor disturbances (particularly nystagmus and tonic upgaze deviation), and progressive cerebellar atrophy." (PMID 34708008, 2021).
congenital disorder of glycosylation type 1a (13 papers, 2013 to 2025). "PMM2 encodes phosphomannomutase-2 that has been associated with congenital disorder of glycosylation type 1a (MIM #212065)." (PMID 30961659, 2019). "Congenital disorder of glycosylation type 1a is an inherited metabolic disorder associated with mutations in PMM2 gene and can affect almost all organs." (PMID 29361989, 2018). "Here, we describe an Iranian family with three individuals affected by the rare congenital disorder of glycosylation type 1a, who have a compound heterozygote variant in the PMM2 gene; it is the third family with PMM2-CDG reported from Iran with a new nucleotide substitution." (PMID 40886090, 2025). "In particular, variants in the PMM2 gene have been proved to contribute to defects in the protein glycosylation pathway, manifesting as carbohydrate-deficient glycoprotein syndrome type I (congenital disorders of glycosylation, type 1a, CDG1a), with CDG1a the most common CDG disorder." (PMID 36726472, 2022). "PMM2-CDG, also known as congenital disorder of glycosylation type 1a, is the most common N-linked glycosylation disorder, characterized by a wide range of neurological and multisystem manifestations." (PMID 40886090, 2025). "Phosphomannomutase 2 deficiency (PMM2-CDG) is the most common congenital disorder of glycosylation, and was originally described in the literature as CDG1a/CDG1/Jaeken Syndrome." (PMID 30530630, 2019). "Congenital disorder of glycosylation type Ia (CDG-Ia1, recently named PMM2-CDG) is an inherited autosomal recessive rare disease caused by mutations in the phosphomannomutase 2 (PMM2) gene and affected more than 800 patients worldwide in 2009 (calculated frequency 1:20.000 to 1:50.000 births)." (PMID 26785728, 2016). "PMM2-CDG, also known as CDG-1A or Jaeken syndrome, is a rare autosomic recessive disease without a cure." (PMID 31454904, 2019). "PMM2-CDG (MIM#212065), also known as CDG-1A or Jaeken syndrome, is an autosomic recessive disease without a cure." (PMID 29261720, 2017).
polycystic kidney disease (11 papers, 2017 to 2025). A usually autosomal dominant and less frequently autosomal recessive genetic disorder characterized by the presence of numerous cysts in the kidneys leading to end-stage renal failure. "Recently, PMM2 (phosphomannomutase 2) mutation has been associated with HH, especially in conjunction with polycystic kidney disease (PKD)." (PMID 36412659, 2022). "A remarkable variant is the PMM2 promoter defect c.-167G>T, homozygous or in trans with PMM2-coding variants, resulting in a very restricted phenotype of polycystic kidney disease (and liver cysts in half of them) and hyperinsulinaemic hypoglycaemia." (PMID 33554500, 2020). "We report the first case of AION in a 2-year 11-month-old child receiving chronic hemodialysis secondary to polycystic kidney disease from a phosphomannomutase 2 gene mutation." (PMID 32257471, 2020). "The phosphomannomutase 2 gene (PMM2) has recently been reported to cause HH as well as congenital polycystic kidney disease in 17 children from 11 unrelated families." (PMID 28855921, 2017). "The enzyme PMM2 is involved in glycosylation and the PMM2 gene has recently been reported to cause HH as well as congenital polycystic kidney disease in 17 children from 11 unrelated families." (PMID 29280746, 2017). "presented another case of CHI and polycystic kidneys with that particular PMM2 variant." (PMID 37065762, 2023). "Its mutation in humans leads to various kinds of diseases, including PMM2-CDG, glaucoma, hyperinsulinemic hypoglycemia, polycystic kidney disease, and premature ovarian insufficiency." (PMID 36743691, 2023).
Cerebellar atrophy (9 papers, 2013 to 2025). Cerebellar atrophy is defined as a cerebellum with initially normal structures, in a posterior fossa with normal size, which displays enlarged fissures (interfolial spaces) in comparison to the foliae secondary to loss of tissue. "ICARS scores correlated with NCRS and were higher in patients with severe PMM2 variants and severe cerebellar atrophy." (PMID 38308356, 2024). "We aimed to identify clinical, molecular and radiological correlates of activities of daily living (ADL) in patients with cerebellar atrophy caused by PMM2 mutations (PMM2-CDG), the most frequent congenital disorder of glycosylation." (PMID 33619652, 2021). "Other PMM2-CDG patients reported so far with a mild phenotype had cerebellar atrophy associated with mild to moderate ID, even when diagnosed in adulthood." (PMID 25497157, 2014). "Based on these results, we suggest that in addition to cerebellar atrophy, the occurrence of brainstem atrophy should be considered among outcome predictors in patients with PMM2-CDG." (PMID 33619652, 2021). "PMM2-CDG patients typically show different degrees of cerebellar atrophy on MRI, mostly vermian atrophy." (PMID 33133147, 2020). "PMM2-CDG is a rare autosomal recessive disease characterized by multisystemic dysfunction, including cerebellar atrophy, peripheral neuropathy, developmental delay, and coagulation abnormalities." (PMID 40572562, 2025). "Additionally, our findings add weight to the view that PMM2-CDG may be diagnosed in teenage/adult patients with cerebellar atrophy, even in the absence of intellectual deficiency or non-neurological involvement." (PMID 25497157, 2014). "Patients with the most common CDG type, PMM2-CDG, develop cerebellar atrophy/hypoplasia, in which significant numbers of cerebellar Purkinje cells and granule cells are lost." (PMID 24305089, 2013).
developmental delay (7 papers, 2014 to 2025). "Second, the glycosylation disorder, PMM2-CDG, is caused by mutations in PMM2 and presents clinically with developmental delay, psychomotor retardation, and axial hypotonia, among other symptoms." (PMID 39773880, 2025). "PMM2-CDG clinical spectrum is primarily characterized by neurological manifestations (such as developmental delay, intellectual disability and seizures), ocular defects, endocrine abnormalities and failure to thrive." (PMID 41425985, 2025).